MIR1281 (microRNA 1281)
Synonyms: hsa-mir-1281; MIRN1281
Gene: MicroRNA gene on chromosome 22 (41,092,513 to 41,092,566, forward strand). Ensembl gene ENSG00000284015.
Diseases named in the same sentence as MIR1281 in open-access papers:
MIR1281 is named in the same sentence as 1 disease in open-access papers, as found by Europe PMC text mining. Sharing a sentence is not in itself a finding about the gene and the disease. The quoted sentences say what the papers report.
cancer (2 papers, 2021 to 2023). A tumor composed of atypical neoplastic, often pleomorphic cells that invade other tissues. "Among the 850 hypoxia-related genes, 6 genes (LOC101928143, LOC102723407, MIR1281, PLA2G4B, SLC5A10, and G6PC1) were absent from the TCGA pan-cancer RNA-seq data; thus, 844 genes with RNA expression values were used in the analysis." (PMID 38248716, 2023).